GNA11 (G protein subunit alpha 11)
Diseases named in the same sentence as GNA11 in open-access papers (continued):
Sharing a sentence is not in itself a finding about the gene and the disease.
uveal melanoma (continued). "In summary, this is the first meta-analysis of driver mutations in uveal melanoma, showing that BAP1 mutations are linked to an increased risk of metastatic disease in uveal melanoma, while no such association was observed with GNAQ/GNA11 and SF3B1 mutations." (PMID 39061150, 2024). "This combination could improve the survival of metastatic uveal melanoma patients while waiting for the development of specific GNAQ and GNA11 inhibitors and in the rarer cases of GNAQ/11 wild-type metastatic uveal melanoma." (PMID 36765842, 2023). "Uveal melanomas driven by mutant GNAQ/GNA11 (Gαq proteins) activate FAK through TRIO-RHOA non-canonical Gαq; FAK, in turn, activates YAP, which promotes aberrant uveal melanoma growth." (PMID 35159327, 2022). "We initially examined TNFα signaling in response to exogenous TNFα in 40 melanoma cell lines, including 31 cutaneous (11 BRAF-mutant, 10 NRAS-mutant, 10 BRAF/RAS WT) and nine uveal melanoma cell lines (five GNAQ-mutant, three GNA11-mutant and one GNAQ/GNA11 WT)." (PMID 34073253, 2021). "Some cases presented with mutations usually linked to uveal melanomas (GNAQ, GNA11, SF3B1, BAP1), but these mutations did not co-occur, suggesting a different tumorigenesis process than in UM." (PMID 34359736, 2021). "Third, the majority of uveal melanoma is driven by mutations in GNAQ and GNA11, as opposed to Braf and Nras mutations in cutaneous melanoma." (PMID 31320995, 2019). "In the 80 uveal melanoma samples, 50% had GNAQ and 44% had GNA11." (PMID 31598164, 2019). "Moreover, the combination of MEK1/2 inhibitors with dual PI3K/MTOR inhibitors, or PKC inhibitors, enhanced uveal melanoma cell death in a mutant GNAQ- and GNA11-dependent manner." (PMID 27057633, 2016). "Koopmans and his colleagues reported that patient survival in uveal melanoma was not correlated with oncogenic mutations in GNAQ and GNA11." (PMID 25280020, 2014). "Unlike skin melanomas, BRAF mutations are extremely rare in uveal melanomas, where the vast majority show mutations in the genes GNAQ and GNA11 that activate the mitogen-activated protein kinase (MAPK) pathway and, consequently, result in increased cell proliferation." (PMID 32911759, 2020). "Uveal melanoma without G protein mutations appears less sensitive than GNAQ and GNA11 mutant cells." (PMID 31320995, 2019). "Although uveal melanoma does not express direct changes in the BRAF gene (rendering its indication of vemurafenib and dabrafenib unfeasible), it has mutations in the GNAQ or GNA11 (G protein subunit encoding) genes within 80% of cases." (PMID 28573105, 2017). "A recent study reported recurrent mutations of G-protein-coupled receptor CYSLTR2 (cysteinyl leokotriene receptor 2) exclusively occurring in uveal melanoma patients not displaying GNAQ, GNA11, and phospholipase C, beta 4 (PLCB4) mutations (in about 40% of these patients)." (PMID 29156643, 2017). "Neither GNAQ nor GNA11 mutant uveal melanoma cell lines were tested in that study." (PMID 24551032, 2014).
melanoma (85 papers, 2011 to 2025). A malignant, usually aggressive tumor composed of atypical, neoplastic melanocytes. "In our previous work, we identified an oncogenic driver mutation in the Gna11 gene of the HCmel12 mouse melanoma cell line." (PMID 38360887, 2024). "Blue naevi are presented as rare dermal melanocytic neoplasms characterized by GNAQ/GNA11 mutations, which very infrequently progress to melanoma." (PMID 36140455, 2022). "Recently, of the 11,111 patients screened, 117 patients have been found to harbour GNAQ/GNA11 mutations, in melanoma, colorectal, liver, glioma, lung, bile duct and gastric cancers." (PMID 35975235, 2022). "In conclusion, our findings strongly nominate the rare CYSLTR2 p.L129Q mutation as an early oncogenic event in GNAQ and GNA11 wild-type uveal nevi and melanomas." (PMID 33588787, 2021). "Using GNA11 mutated melanoma cell lines, MEK inhibitors to suppress MAPK pathways, and suppressing protein kinase C led to the synergistic inhibition of proliferation." (PMID 32373524, 2020). "While GNAQ and GNA11 mutations were recently reported to occur in 9.5% of mucosal melanomas, our study suggests these mutations are less frequent in this tumor entity." (PMID 28380455, 2017). "Van Raamsdonk and her colleagues reported that GNA11 mutations were more common in locally advanced primary tumors and in melanomas originating from the peripheral choroid or ciliary body." (PMID 25280020, 2014). "However, some other studies on GNA11 mainly focus on the influence of its mutation on melanoma, and there are few studies working on GNA11 in ESCC." (PMID 34568004, 2021). "In a case submitted for analysis as melanoma from an unknown cutaneous primary site, metastatic to the T10 intradural space, our profiling identified GNA11 Q209L mutation." (PMID 25415047, 2014). "In this study, as an extension to our previous work on head and neck mucosal melanomas, we aimed to investigate the BRAF, NRAS, KIT, TERT and GNAQ/GNA11 mutation status of 15 AMs, as well as their clinicopathologic features." (PMID 35642348, 2023). "Acral melanomas harbor KIT, NRAS, and BRAF mutations, mucosal melanomas KIT and NRAS mutations, and uveal and melanomas arising in blue nevi uniquely have GNA11 and GNAQ mutations." (PMID 37841001, 2023). "In recent years, advances in whole genome sequencing technology have unearthed a previously unappreciated widespread role of GNA11 in melanomas." (PMID 37396036, 2023). "Several genes have been identified as genetically altered drivers of melanoma tumorigenesis, such as NRAS, CDNK2A, MITF, PTEN, KIT, GNAQ, GNA11 or CTNNB1, but most (60%) melanomas have BRAF gene mutations." (PMID 35326682, 2022). "All these melanomas were wild-type for CYSLTR2 and the majority carried mutations in GNAQ, GNA11 or PLCB4." (PMID 33588787, 2021). "We found that the nevogenic melanomas were associated with mutations in BRAF, while the CSD melanomas were associated with mutations in NF1, ROS1, GNA11, and RAC1." (PMID 34680367, 2021). "A retrospective study investigating 93 melanomas found a higher rate of BRAFV600E mutations (40%), while a few genetic reports of single cases showed recurrent Q209L change on the GNA11 gene." (PMID 33525348, 2021). "The CSD melanomas, in contrast, showed mutations in a diverse group of genes that included NF1, ROS1, GNA11, and RAC1." (PMID 34680367, 2021). "As recently reported, potential markers in melanoma are mutations (on BRAF, NRAS, KIT, GNA11/GNAQ, NF1, CDKN2AI, immunohistochemical biomarkers (such as PD-11 and PD-L1, as well as mutated BRAF and NY-ESO-1), miRNAs, and other serum molecules." (PMID 33302400, 2020).
melanoma (continued). "The author also identified RasGRP3 expression specifically in Gnaq/Gna11-driven melanoma and observed that RasGRP3 is required for Gnaq/Gna11-driven RAS activation." (PMID 32532044, 2020). "It is thought that mutations in SF3B1 arise as a second genetic change in UM and blue nevus-like melanoma, after initial mutation in GNAQ or GNA11; however, SF3B1 changes can be driver mutations in MDS." (PMID 30558566, 2018). "In this study, we examined POM for alterations in candidate melanoma driver genes (BRAF, NRAS, KRAS, GNA11, GNAQ) and genes implicated in UM prognosis (EIF1AX, SF3B1, BAP1)." (PMID 30558566, 2018). "MLPA was conducted to detect chromosomal alterations and Sanger sequencing used to identify point mutations in candidate melanoma driver genes (BRAF, NRAS, KRAS, GNA11, GNAQ), and other genes implicated in melanoma prognosis (EIF1AX, SF3B1)." (PMID 30558566, 2018). "Melanoma-related A to T transversion in GNA11 (G protein subunit alpha 11) gene leading to a G209 L substitution is a “somatic variation” (VariO:0446)." (PMID 30591019, 2018). "As expected, the RAS pathway was mutated in the majority of melanomas (89%) and the MAPK pathway (GNA11 and GNAQ) in 4% of melanomas, displaying a mutually exclusive pattern with mutations in the RAS pathway (P = 0.001)." (PMID 28267273, 2017). "Lovly and coworkers have developed a melanoma-specific multiplex mutational profiling assay to detect the 43 recurrent mutations occurring in 6 genes frequently mutated in melanomas: BRAF, NRAS, KIT, GNAQ, and GNA11." (PMID 29156643, 2017). "Of the 19 non‐sun‐induced melanomas in the cohort (uveal, n = 2; acral/mucosal, n = 17), only four cases contained recurrent mutations in KIT or GNA11." (PMID 28267273, 2017). "Some mutations present in melanoma, such as BRAF, NRAS, GNAQ, or GNA11, and rearrangements in fusion kinases, have been observed in benign nevi, and therefore represent events acquired early during tumor progression." (PMID 29156643, 2017). "Approximately 75% of melanomas have known driver oncogenic mutations in BRAF, NRAS, GNA11 or GNAQ, while the mutations providing constitutive oncogenic signaling in the remaining melanomas are not known." (PMID 27273450, 2016). "In this report choroidal, ciliochoroidal and iridociliary melanomas were analyzed for GNAQ and GNA11 mutations which were subsequently correlated to the location of tumor origin." (PMID 26368812, 2015). "The optimum treatment for other subsets, including NRAS-, GNAQ- or GNA11-mutant melanomas, remains to be determined." (PMID 26084293, 2015). "The mutational status of BRAF, RAS, GNAQ, GNA11 and KIT genes in Grey horse melanomas was determined by direct sequencing." (PMID 25413220, 2014). "We confirmed the previously reported cytotoxic effect of a MEK inhibitor against cell lines with BRAFV600E mutations, but in addition the cytotoxic activity was evident in a high proportion of melanoma cell lines with NRAS, GNAQ or GNA11 driver mutations." (PMID 22515704, 2012). "Another MEK1/2 inhibitor, GSK1120212, is in Phase II for BRAF-mutant melanoma as well as for melanomas with GNAQ and GNA11 mutations." (PMID 21479172, 2011). "Recent years have seen the emergence of promising therapies, including tebentafusp, which stimulates immune responses against gp100-expressing melanoma cells, and darovasertib, a potent PKC inhibitor that targets MAPK pathway activation driven by GNAQ/GNA11 mutations." (PMID 40565803, 2025). "The standard four-probe FISH assay should not be applied to tumors for which melanoma arising in blue nevus is a consideration because genomic CNAs typically observed in melanoma arising in blue nevus (GNAQ and GNA11) are different than those of the typical melanoma pathways." (PMID 38247727, 2024). "For example, nearly one-half of melanomas arising in the epidermis harbor oncogenic mutations in the BRAF gene, while almost half of the melanomas arising in the uvea harbor oncogenic mutations in the GNAQ/GNA11 genes." (PMID 38360887, 2024).
melanoma (continued). "Previously, ‘driver-negative’ (i.e. the absence of BRAF, NRAS, KIT, GNAQ or GNA11 mutations) melanoma cell-lines that were less sensitive to trametinib and which displayed paradoxical activation of MEK1/2, were found to show basal EGFR activation due to AREG." (PMID 35993275, 2022). "Several prominent genes mutated in CSD melanomas included NF1, ROS1, GNA11, and RAC1." (PMID 34680367, 2021). "In the future, the identification of the epidermal signals that restrain the GNAQQ209L oncogene could suggest novel therapies for GNAQ and GNA11 mutant melanomas." (PMID 34939927, 2021). "Furthermore, for mutated genes normally related to non‐sun‐induced melanomas (KIT, GNA11, GNAQ), we found that KIT and GNA11 were enriched in the triple‐wild‐type group (FDR < 0.001 or 0.01, respectively)." (PMID 28267273, 2017). "Finally, other less frequently mutated melanoma genes (KRAS, HRAS, KIT, GNAQ, GNA11) were enriched in tumors wild‐type for BRAF, NRAS, and NF1." (PMID 28267273, 2017). "Spitz tumors generally lack mutations in oncogenes classically associated with melanoma, such as NRAS, KIT, GNAQ, and GNA11, though distinct histopathologic forms have been found to harbor BRAFV600E and HRAS mutations, and suggest a role for activating kinase pathways in tumorigenesis." (PMID 28895885, 2017). "In this article, we first briefly outline the function of G protein coupled receptors in cancer, and then specifically examine the roles of the seven transmembrane G protein coupled Endothelin B receptor (Ednrb) and the G proteins, GNAQ and GNA11, in both melanocyte development and melanoma." (PMID 27148356, 2016). "Melanomas are characterized by activating “driver” mutations in BRAF, NRAS, KIT, GNAQ, and GNA11." (PMID 26084293, 2015). "Furthermore, PI3KCA activating mutations common in many cancers have been detected in ≤3% of melanomas, while recently GNAQ/GNA11 mutations have been detected in uveal melanomas in up to 34–48% compared to <1% of cutaneous melanomas." (PMID 25695059, 2015). "We report here development, validation, and implementation of an assay designed to simultaneously detect 43 common somatic point mutations in 6 genes (BRAF, NRAS, KIT, GNAQ, GNA11, and CTNNB1) potentially relevant to existing and emerging targeted therapies specifically in melanoma." (PMID 22536370, 2012). "In contrast, the CSD melanomas had a higher frequency of mutations than the nevogenic melanomas in NF1 (14/37, 37.8% vs. 6/82, 7.3%; p < 0.001), ROS1 (10/37, 27.0% vs. 4/82, 4.9%; p = 0.001), GNA11 (4/37, 10.8% vs. 1/82, 1.2%; p = 0.032), and RAC1 (6/37, 16.2% vs. 1/82, 1.2%; p = 0.004)." (PMID 34680367, 2021). "The underlying mechanism for the restriction of GNAQ and GNA11 mutations to non-epithelial melanomas is unknown." (PMID 34939927, 2021). "It is possible that a better understanding of the ability of GNAQQ209L to switch from acting as an oncogene to an inhibitor of melanocyte growth could lead to new therapies for GNAQ and GNA11 mutant melanomas, which lack effective treatment options for metastatic disease." (PMID 34939927, 2021). "Thus, CRAF is a bona fide alternative oncogene for BRAF/NRAS/GNAQ/GNA11 wild type melanomas." (PMID 27273450, 2016). "However, treatment options remain limited for the patients that lack mutations in the five most commonly mutated melanoma genes (BRAF, NRAS, KIT, GNAQ and GNA11) and the prognosis of such patients is particularly pool with a median overall survival of less than 1 year." (PMID 26424083, 2015).
melanoma (continued). "At least 6 genes have been shown to be recurrently mutated in melanoma, including the serine-threonine kinase encoded by BRAF; the receptor tyrosine kinase encoded by KIT; the GTP-binding proteins encoded by NRAS, GNA11, and GNAQ; and the WNT signaling pathway component encoded by CTNNB1." (PMID 22536370, 2012). "However, GNAQ or GNA11 mutations have never been reported in this type of melanoma." (PMID 39804140, 2025). "Gene mutations are often involved in tumorigenesis, the clustered deletions were found in ABL1, NOTCH1, RET, STK11, GNA11, and JAK3 genes in CRC, melanoma, and non-small cell lung cancers." (PMID 32850446, 2020). "A typical example of a genomic panel recommended for cancer diagnosis is a panel comprising of BRAF, KIT, NRAS, GNA11 and GNAQ for Melanomas." (PMID 23863689, 2013). "Several oncogenes have been identified in melanoma as BRAF, NRAS, c-Kit, and GNA11 GNAQ, each capable of activating MAPK pathway, although NRAS and c-Kit also activate PI3 kinase pathway, including being more commonly BRAF activated oncogene." (PMID 23476798, 2013). "In exceedingly difficult cases, molecular and genomic analysis can also be beneficial, as melanoma arising in blue nevi do not typically exhibit BRAF mutations, but rather GNAQ, GNA11, PLCB4, or CYSLTR2 mutations." (PMID 40843873, 2025). "Comprehensive molecular profiling, including common melanoma-associated mutations in BRAF, NRAS and the GNAQ/GNA11 signaling pathway, was not performed in this case." (PMID 41294657, 2025). "It has been reported, that NTRK fusions and typical oncogenic drivers, such as BRAF, NRAS, GNAQ and GNA11 are mutually exclusive and NTRK fusions might be more common in BRAF or NRAS wild-type melanomas." (PMID 35993275, 2022). "Sequencing of mutation hotspots in five melanoma driver genes (BRAF, NRAS, KRAS, GNAQ, GNA11) did not reveal any changes in 9/11 patients." (PMID 30558566, 2018). "Among 253 melanomas, 129 (51.0%) BRAF, 45 (17.8%) NRAS, 6 (2.4%) KIT, 4 (1.6%) GNAQ, 2 (0.8%) GNA11, 2 (0.8%) MAP2K1 and no MAP2K2 gene mutations were detected by the biochip assay." (PMID 28881731, 2017). "We defined “pan-negative” samples as those melanomas harboring none of the well-known, specific, and recurrent mutations in the genes BRAF, NRAS, KIT, GNAQ, or GNA11, which are commonly mutated in melanoma." (PMID 25537510, 2015). "The present study also shows that somatic activating BRAF, RAS, GNAQ, GNA11 and KIT mutations, frequently observed in human melanomas, are not required for melanoma development in Grey horses." (PMID 25413220, 2014). "Two of these four melanomas had mutations in NF1, one in KIT and one in GNA11 (data not shown)." (PMID 36077603, 2022). "Hence, gain-of-function mutations in GNAQ, GNA11, or PLCB4 only drive melanoma in melanocytes surrounded by mesenchymal stromas, and not by keratinocytes." (PMID 34939927, 2021). "We found that the ERK pathway is constitutively activated in Grey horse melanoma tumours and cells in the absence of somatic oncogenic mutations in BRAF, RAS, GNAQ, GNA11 and KIT that are associated with activation of this pathway in the majority of human melanocytic tumours." (PMID 25413220, 2014). "We found that the ERK pathway is constitutively activated in Grey horse melanoma tumours and cell lines in the absence of somatic activating mutations in BRAF, RAS, GNAQ, GNA11 and KIT genes or alterations in the expression of the main components of the pathway." (PMID 25413220, 2014).